IL5 (interleukin 5)
Diseases named in the same sentence as IL5 in open-access papers (continued):
Sharing a sentence is not in itself a finding about the gene and the disease.
Obesity (continued). "Other authors found increased IL-5 levels in medication-free MDD patients and MDD patients with or without obesity as comorbidity." (PMID 35455402, 2022). "We found higher levels of IL-5 in NOA subjects with respect to HC and O individuals, but we could not find any additive effect of obesity in OA patients." (PMID 35807067, 2022).
colitis (58 papers, 2011 to 2025). Inflammation of the colon. "Here, our data suggest that the deficiency of Mcpt-4 triggered a stronger Th2 response in colitis as manifested by increased levels of IL-4, IL-5, IL-10, and IL-13, whereas IL-10 is also generally known as an anti-inflammatory cytokine." (PMID 40697820, 2025). "In dextran sodium sulfate (DSS)-induced colitis, IL-5, the hallmark cytokine of ILC2s, was significantly reduced, while the type I interferon (T1IFN) signature was enriched." (PMID 36268010, 2022). "IL-5 levels were lower in the amygdala of animals possessing an A allele following colitis than either the A allele saline group or the C allele colitis group." (PMID 34916909, 2021). "The delayed early kinetic of DSS-induced colitis symptoms in IL-5-deficient mice is reversed by reconstituting the mice with H4R+/+ eosinophils." (PMID 30319608, 2018). "Reconstitution of IL-5-deficient mice with eosinophils led to an aggravation of DSS-induced clinical signs of colitis, the H4R+/+ eosinophils' transfer resulting in an earlier onset and a faster enhancement of the DAI than the H4R−/− eosinophils' transfer." (PMID 30319608, 2018). "During the 1-week observation period, transfer of eosinophils transiently reversed the acute clinical colitis-like phenotype (body weight loss, perianal bleeding, soft stool consistency) resulting from IL-5-deficiency." (PMID 30319608, 2018). "Th1 and Th2 cytokines, such as interferon-γ (IFN-γ), interleukin-4 (IL-4), and interleukin-5 (IL-5), are closely associated with the pathogenesis of colitis induced by DSS." (PMID 29888292, 2018). "Type-2 gut inflammation is not driven by IL-12 and IFN-γ, but is thought to be caused by elevated levels of IL-4, IL-5, and IL-13 and studies have shown a delay in the onset of colitis when IL-4 is blocked by a neutralizing anti-IL-4 antibody." (PMID 22539101, 2012). "(50, 100, 200 mg/kg) could protect against the TNBS-caused colitis in a rat model by decreasing the levels of IL-33, IL-5, IL-13, IL-6 cytokines and expression of IL-33 and ST2 proteins to inhibit the IL-33/ST2 signaling pathway." (PMID 36160392, 2022). "Indeed, two previous studies analyzing DSS-induced colitis using IL-5-deficient mice concluded that IL-5 alone plays a minor role in the DSS model, whereas we observed a modestly more robust effect in our study." (PMID 30930900, 2019). "These modest effects of IL-5 deficiency on DSS colitis may be due to eosinophils providing both pro- and anti-inflammatory functions during intestinal inflammation, as well as the use of IL-5-deficient mice in these studies and antibody-mediated IL-5 neutralization in our study." (PMID 30930900, 2019). "Perilla seed oil, rich in α-linolenic acid, reduces colitis by suppressing inflammatory markers including interleukin-1 (IL-1), interleukin-2 (IL-2), interleukin-4 (IL-4), interleukin-5 (IL-5), interleukin-6 (IL-6), and interleukin-10 (IL-10)." (PMID 39022021, 2024). "Th2 cells, in contrast, are characterized by their secretion of interleukin-4 (IL-4), interleukin-5 (IL-5), and interleukin-13 (IL-13), which can contribute to the transition from colitis to cancer." (PMID 39575712, 2024). "An examination of the expression levels of inflammatory cytokines involved in intestinal inflammation in OXAC confirmed that colitis, which demonstrates a pattern of hypersecretion of IL-5 and IL-13, was induced." (PMID 38732497, 2024). "Regarding the mechanism by which uPA inhibition reduces inflammation, we found that concentrations of RANTES, IL-12 (p40), GM-CSF and IL-5 in colitis tissue were significantly reduced in uPA−/− mice." (PMID 36806262, 2023). "The qRT-PCR results showed that IL-4, IL-5, and IL-13 levels were significantly higher in the intestinal mucosa of colitis-induced mice than those in the control group (p < 0.05)." (PMID 36359214, 2022).
colitis (continued). "After administration of SI, IL-4, IL-5, and IL-13 levels were significantly reduced in the colonic mucosa of SI-treated mice compared to those in the colitis group (p < 0.05)." (PMID 36359214, 2022). "On the contrary, an increase of CCR3+SSCHI eosinophils in the spleen was observed in IL-5 transgenic mice subjected to DSS-induced colitis." (PMID 35887133, 2022). "We also confirmed that colonic ILC2s obtained from DSS-induced colitis mice showed significantly reduced IL-5 production only when stimulated with IL-25 and IL-33 alone or in combination." (PMID 36268010, 2022). "Our data suggests that ILC2s show enhanced production of genes related to T1IFN responses and a reduction in IL-5 production in colitis." (PMID 36268010, 2022). "Early transgenesis of IL-5 in colitis-assosiated CRC mouse model increased the severity of colitis, induced the rate of polyps formation and as a result higher tumor load." (PMID 34631734, 2021). "Indeed, injecting rmIL-33 into mice suffering from acute DSS colitis, strongly abrogated epithelial damage, pro-inflammatory cytokine secretion, and loss of barrier integrity, while it induced a strong increase of Th2 associated cytokines (IL-13/IL-5) in the colon." (PMID 34335571, 2021). "Nevertheless, the effect of melatonin on type 2 immunity-dependent colitis needs to be documented, as levels of type 2 cytokines, including IL-5 and IL-13, increase in UC patients." (PMID 35116024, 2021). "Neutralizing IL-5 in mice reduced eosinophil numbers and diminished the inflammation associated with DSS-induced colitis." (PMID 32010138, 2019). "We next examined the effects of these 4 different treatments (control IgG, IL-2/JES6-1 immunocomplexes alone, anti-IL-5 mAb alone, and IL-2/JES6-1 immunocomplexes + anti-IL-5 mAb) on DSS-induced colitis and recovery." (PMID 30930900, 2019). "In line with this, we found that Th17 (CD4+IL-17A+) and Th2 (CD4+IL-4+ and CD4+ IL-5+) obviously decreased in IL-21RKO mice with DSS-induced colitis." (PMID 27545302, 2016). "A differential effect of GM-CSF and IL-5 was also evident on the “gut-tagging” of newly produced BM eosinophils, as upregulation of α4β7 integrin in colitis was only inhibited by IL-5 blockade." (PMID 26200014, 2015). "Treatment with anti-mouse Siglec-F immune serum reduced colitis severity to the same extent as IL-5 blockade." (PMID 26200014, 2015). "Annexin-V staining on freshly isolated peripheral eosinophils was decreased in colitis and increased in the presence of GM-CSF or IL-5 blockade." (PMID 26200014, 2015). "Although both cytokines promoted eosinopoiesis during colitis, IL-5 specifically increased the differentiation of EoPs into Siglec-F+ eosinophils and promoted imprinting of α4β7 integrin expression." (PMID 26200014, 2015). "IL-5 blockade or eosinophil depletion ameliorated colitis, implicating eosinophils in disease pathogenesis." (PMID 26200014, 2015). "It has been previously demonstrated that the overexpression of IL-5 significantly increases the severity of OXA-induced colitis." (PMID 25187824, 2014). "Anti-IL-5 therapy showed therapeutic potential in experimental colitis." (PMID 40498001, 2025). "Colitis can activate Th1 cells, resulting in the release of Th1-related cytokines such as IFN-γ, while ulcerative colitis is associated with Th2 and the release of IL-5, IL-13, and IL-9." (PMID 35240996, 2022). "Interestingly, upon colitis induction, IL-5 mRNA was significantly reduced only in DSS-treated GAL3R-WT mice compared to corresponding controls (p = 0.034) but was not influenced by DSS in any other group." (PMID 33436730, 2021). "Owing to Oxa-induced colitis being mediated by type 2 immunity, the effect of melatonin on the secretion of type 2 inflammatory cytokines was assessed, and melatonin treatment markedly suppressed the production of IL-5 and IL-13 in the colon of the MT50 group." (PMID 35116024, 2021).
colitis (continued). "Mice with DSS induced colitis receiving anti-IL-5 treatment exhibited lower eosinophil expression, more severe weight loss and higher hemoccult scores indicating that IL-5, and eosinophils, may possibly play a protective role in colitis development as well." (PMID 34737752, 2021). "IL-5-mediated eosinophil activation has been related to colitis development, which may explain the elevated levels of IL-5 in the blood of Atg5ΔFoxp3 mice." (PMID 34512629, 2021). "Furthermore, cLP ILCs from T-betΔNCR+ILC DSS-colitis mice produced higher IL-13 and IL-5 after stimulation than ILCs from DSS-WT mice, whereas IL-17A and IFNγ production by ILCs were equivalent in both groups." (PMID 30356098, 2019). "IL-5-deficient BALB/c mice served as a model with reduced endogenous numbers of eosinophils, in which wild-type (H4R+/+) or H4R-deficient (H4R−/−) eosinophils were adoptively transferred during the course of DSS-induced colitis." (PMID 30319608, 2018). "Our previous results have shown that prevention of colitis by immunization with P28GST in the presence of adjuvant was associated with Th2-type regulatory processes such as eosinophil recruitment in lamina propria or increased IL-13 and IL-5." (PMID 30592734, 2018). "Indeed, via cytokine Th2 production (IL-4, IL-5 and IL-13), they counterbalance the hyper reactive Th1 / Th17 response induced in colitis." (PMID 30592734, 2018). "Hence, the disease-aggravating effect of IL-5 on acute DSS-induced colitis indeed depends on the genetic background of the mouse model employed." (PMID 30319608, 2018). "Although in mice lacking IL-5 expression the infection-induced enhancement of eosinophil numbers is abolished, IL-5 deficiency is reported to be without effect on the pathogenesis of acute DSS-induced colitis." (PMID 30319608, 2018). "Hence, in this study we adoptively transferred eosinophils from H4R-deficient (H4R−/−) and H4R-competent, i.e. wild-type (H4R+/+) mice into IL-5-deficient BALB/cJ mice and thereafter subjected these reconstituted mice to DSS-induced colitis." (PMID 30319608, 2018). "As noticed above we observed particularly in DNBS-induced colitis an increase of IL-5, IL-17 and IFNγ in colon tissue of mice treated with LL-pILEMPTY compared to control group and a tendency to decrease IL10 even if the difference is not statistically significant." (PMID 28203226, 2017). "As GM-CSF production was increased during colitis, while IL-5 levels stayed constant, we hypothesized that GM-CSF would be a key driver of eosinophil effector functions in the inflamed intestine." (PMID 26200014, 2015). "Interestingly CD64 (FcγRI), which is increased on neutrophils in IBD, was induced on eosinophils during colitis in a GM-CSF-dependent but IL-5-independent manner." (PMID 26200014, 2015). "IL-4 and IL-5 expressions were previously quantified in intestinal tissue and correlated with the clinical and histological severity of colitis in UC patients, and IL-13, which was also found to be up-regulated in UC, was linked to an impaired epithelial barrier function in the gut." (PMID 22539101, 2012). "We demonstrate that IL-5 deficiency in BALB/cJ mice is protective against DSS-induced colitis and that adoptive transfer of eosinophils into these mice transiently reverts the acute colitis phenotype, eosinophils from H4R+/+ mice being more efficient than those from H4R−/− mice." (PMID 30319608, 2018). "However, intestinal IL-5 does not appear to be controlled by IL-23 because IL-5 expression was not increased in colitis or reduced in IL-23 deficiency." (PMID 26200014, 2015). "The levels of IL-4, IL-5, IL-17, and CCL11 were increased in the TA-administered colitis group compared with the unadministered colitis mice, but this increase was not statistically significant." (PMID 40333150, 2025). "IL-5 promotes eosinophil production through IL-5Rα and contributes to the pathogenesis of IBD, while IL-5 receptor antagonists alleviate DSS colitis." (PMID 40333150, 2025).
colitis (continued). "Colonic tissues from DSS-induced colitis mice with Blastocystis ST4 colonization demonstrated increased expression of Th2 (IL-4, IL-5, and IL-13) cytokines relative to control mice." (PMID 35435504, 2022). "Synergistically, Rg3-RGE + PT inhibited expression of NO, iNOS, COX-2, IL-1β, IL-6, IL-5, IL-13, and TNF-α in the DSS-induced colitis mice’s macrophage cells, plasma, and colon tissue." (PMID 33182623, 2020). "Increased levels of Flii also resulted in exacerbation of both Th1 and Th2 immune responses in colitis-induced mice with significantly greater levels of TNF-α, IFN-γ, IL-5 and IL-13 being observed." (PMID 31488864, 2019). "The Th1 transcription factor T-bet plays a critical role in the development of Th1-driven colitis due to the high expression levels of IFN-γ, while GATA3 is an essential master regulator of Th2 cells for the induction of IL-4, IL-5, and IL-13." (PMID 26347453, 2015). "Those that were upregulated by 1 log fold or higher include IL-9, IL-13, IL-4, IL-17A, IL-5, IL-24, IFN-γ, IL-10, IL-11, and IL-27, many of which are known cytokines involved in the pathogenesis of colitis." (PMID 21365015, 2011). "Similarly, mice receiving anti-IL-5 exhibit reduced eosinophils infiltration and improved DSS-induced colitis symptoms." (PMID 40332187, 2025). "Evelyn Saba and colleagues found that ginsenoside Rg3 (20 mg/kg) could decrease the expression of pro-inflammatory mediators and cytokines including NO, IL-1β, IL-5, IL-13, and TNF-α, and levels of NLRP3 inflammasome in DSS-induced colitis mice." (PMID 36160392, 2022). "In accordance, we found that, after induction of colitis by DNBS, the signaling cascade through transcription factor NF-κB activation was markedly increased, as well as the level of pro-inflammatory cytokines such as IL-5, IL-9, and IL-13." (PMID 35893393, 2022). "Notably, IL-5 and IL-13 were mainly secreted by CD45+Lin−GATA3+ cells in the colon of Oxa-induced colitis, suggesting that ILC2s were the main producers of type 2 cytokines rather than Th2 cells." (PMID 35116024, 2021). "In this report, we show that treatment of mice with IL-2/JES6-1 immunocomplex during DSS-induced colitis promoted Foxp3+ Treg expansion, but also potently stimulated GATA3+ group 2 innate lymphoid cell (ILC2) proliferation and high-level expression of IL-5 in the colon." (PMID 30930900, 2019). "In contrast, but in agreement with increased UC disease severity observed in FliiTg/Tg mice, distal colons of these colitis-induced mice showed an exacerbated immune response with significantly increased expression of Th1 and Th2 cytokines including TNF-α, IFN-γ, IL-5 and IL-13." (PMID 31488864, 2019). "Here, we show that treatment of mice with IL-2/IL-2 antibody (JES6-1) immunocomplex during DSS-induced colitis induced Foxp3+ Treg expansion, but also potently stimulated GATA3+ type 2 innate lymphoid cell (ILC2) proliferation and high-level expression of IL-5." (PMID 30930900, 2019). "Colitis was induced by DSS application in BALB/cJ WT mice and in BALB/cJ IL-5-deficient mice either or not reconstituted with isogenic bone marrow-derived eosinophils." (PMID 30319608, 2018). "Thus, Th2-like immunity characterized by the productions of IL-4 and IL-5 was impaired, whereas Th1-like immunity capable of producing IFN-γ was enhanced in DSS-induced colitis model in IL-21RKO mice." (PMID 27545302, 2016). "The level of Th1 cytokine-IFN-γ was significantly higher, but the levels of Th2 cytokine-IL-4, IL-5 or IL-13, and Th17 cytokine-IL-17A were greatly lower in colonic LP of IL-21RKO mice after DSS-induced colitis as compared with those in C57BL/6 mice (**P < 0.01 or ***P < 0.001)." (PMID 27545302, 2016). "Eosinophil activation and cytokine secretion that accompanied colitis was inhibited by GM-CSF but not IL-5 blockade." (PMID 26200014, 2015).
colitis (continued). "GM-CSF, which can act in synergy with IL-5 to stimulate eosinopoiesis, was also increased in the inflamed colon compared to controls and ∼40% of CD4+ T cells were GM-CSF+ in colitis." (PMID 26200014, 2015). "Our study showed that IL-5 levels in normal and colitis mice did not significantly differ depending on whether TA was administered." (PMID 40333150, 2025). "A 16-gene signature (CARD12, CCL3, CCR3, CXCL1, F5, FAM210B, GADD45A, IL18bp, IL2RA, IL5, IL8, MMP9, PTGS2, SOCS3, TLR9 and UBE2C) was identified from 30 days post-tremelimumab initiation blood that discriminated patients developing grade 0–1 from grade 2–4 diarrhea/colitis." (PMID 30227886, 2018). "Interestingly, IL-5 and GM-CSF were produced at steady state by ILCs but were not increased in lymphocyte-replete colitis." (PMID 26200014, 2015). "The eosinophil driven colitis in those models exhibited increased expression of mucosal GMCSF, eotaxin, and RANTES but not IL5." (PMID 38512959, 2024). "We next assessed the cytokine production in ILC2s and observed that production of IL-5, but not IL-13, was significantly reduced in DSS-induced colitis when stimulated by PMA plus ionomycin." (PMID 36268010, 2022). "Dietary inulin elevated microbiota-derived bile acids, which induced IL-33 expression and promoted the expansion of inflammatory ILC2s that preferentially secrete IL-5 but not AREG, leading to eosinophil accumulation and exacerbation of DSS-induced colitis in mice." (PMID 40498001, 2025).